TLR4 (toll like receptor 4)
Diseases named in the same sentence as TLR4 in open-access papers (continued):
Sharing a sentence is not in itself a finding about the gene and the disease.
hepatitis C (12 papers, 2014 to 2025). "LPS induced apoptosis of HepG2 was inhibited by decreasing expression of TLR4, associated with hepatitis C virus infection." (PMID 32397371, 2020). "Another GWAS study in hepatitis C patients identified polymorphisms in the TLR4 (Toll-like receptor 4) gene as a determinant of fibrosis progression." (PMID 32398673, 2020). "So that the TLR4 expression was higher in the hepatitis C patients group than in the control group." (PMID 39605886, 2024). "Ectopic TLR4 expression in hepatitis-C transgenic mice generated CD133+ tumor-initiating cells and mice with defective TGF-β signaling developed HCC in a TLR4-dependent manner." (PMID 41465346, 2025). "Moreover, small hepatitis B surface proteins (SHBs) in conjunction with β-2-glycoprotein I (β2GPI) upregulated the NF-κB pathway through TLR4/MyD88/IκBα signaling in SMMC-7721 cells, and in hepatitis C, TLR4 plays a major role in the capacity of B cells to activate T cells." (PMID 37345131, 2023).
IgA nephropathy (12 papers, 2014 to 2025). "Specifically, the deficiency of TLR4 can modulate the levels of inflammatory factors in IgA nephropathy." (PMID 36061150, 2022). "In chronic ischemic renal damage and IgA nephropathy, TLR4 also exerts a high level, which was implicated in exacerbated inflammatory response." (PMID 36061150, 2022). "Hsa-miR-630 regulates the production of underglycosylated IgA1 in the tonsils by targeting Toll-like receptor 4 (TLR4) in IgA nephropathy." (PMID 41496911, 2025). "In IgA nephropathy, Notch1 is activated by Toll-like receptor 4 (TLR4) and mediates inflammatory damage of podocytes by activating NF-κB." (PMID 37865763, 2023). "Finally, in immunoglobulin A (IgA) nephropathy, gut microbiome–induced toll-like receptor 4 signaling promotes the production of hypoglycosylated IgA1, a key driver of glomerular injury." (PMID 40636374, 2025). "In addition, the crosstalk between Notch1 and Toll-like receptor 4 (TLR4) signaling regulates the inflammatory response in IgA nephropathy, indicating the potential role of Notch1 pathway activation in podocyte inflammation." (PMID 39598328, 2024). "It has been reported that TLR4 is highly expressed in IgA1 nephropathy, and TLR4 may regulate IL-8 concentrations through the NF-κB pathway to alleviate IgA nephropathy and that." (PMID 36061150, 2022). "The similar elevated TLR4 expression trend has also been tested in IgA nephropathy." (PMID 36061150, 2022). "This indicated that TLR4 signaling mediated the abnormal immunity of IgA nephropathy." (PMID 24926370, 2014).
Immunodeficiency (12 papers, 2008 to 2025). Failure of the immune system to protect the body adequately from infection, due to the absence or insufficiency of some component process or substance. "Although these encouraging results suggest a potential therapeutic role of the TLRs inhibition in IIM, it is well known that the TLR2, TLR4 and MyD88 deficiency implies a severe immunodeficiency." (PMID 32164729, 2020). "It seems possible that continuous activation of monocytes suppresses the expression of TLR-4, contributing to immune deficiency and increased incidence and severity of infections in ESRD population." (PMID 29200664, 2017). "This study aims to explore the immunomodulatory effect of rhCNB on mice with cyclophosphamide (CTX)-induced immunodeficiency through TLR4/MAPK pathway." (PMID 36204132, 2022). "It is important to learn how the longer TLR-4 and other genetic changes in natural hosts prevent the outbreak of the immunodeficiency." (PMID 30001404, 2018). "In summary, rhCNB can effectively improve the immunodeficiency induced by cyclophosphamide, enhance the immune response of the body by enhancing the function of immune organs and the phagocytosis of macrophages, and regulate Th1 and Th2 through the TLR4/MAPK signal pathway." (PMID 36204132, 2022). "The patient could not recover because of his natural immune deficiency and TLR4/MyD88/NF-κB signaling pathway inactivation." (PMID 34454624, 2021). "Notably, from the PPI network, we observed that TNF, STAT3, TLR4, PIK3R1, and HSP90AB1 were significant targets for GAC intervention in CY-induced immunodeficiency." (PMID 37853057, 2023). "The experimental results found that rhCNB could increase the mRNA levels of TLR4, P38, JNK, and ERK in mice with cyclophosphamide-induced immunodeficiency." (PMID 36204132, 2022).
nasal polyps (12 papers, 2005 to 2025). "In respiratory pathologies, S100a9 promotes tissue remodeling of nasal epithelium in chronic rhinosinusitis with nasal polyps and modulates neuroinflammation through TLR4‐dependent pathways." (PMID 40904186, 2025). "Some evidence suggest that the TLR4 signaling pathway is involved in the pathogenesis of CRSwNP by remodeling of nasal polyp." (PMID 38678138, 2024). "Accordingly, You and coworkers also reported a significant TLR4 increase in epithelial/glandular cells of chronic rhinosinusitis, compared to nasal polyps and control tissues." (PMID 22577387, 2012). "On the other hand, mRNA expression of TLR4 has been reported to be significantly increased in chronic rhinosinusitis tissues compared with that in nasal polyps and TLR4 was overexpressed in the epithelium of chronic rhinosinusitis, evaluated by confocal analysis." (PMID 28127565, 2016). "Additionally, we found that expression of IL-6, IL-8, and MMP-1 is stimulated by LPS via TLR4 in nasal polyp organ cultures." (PMID 25390332, 2014). "The aim of this study was to evaluate whether nasal polyp-derived fibroblasts (NPDFs) and organ-cultured nasal polyps can synthesize pro-inflammatory cytokines and matrix metalloproteinases (MMPs) after exposure to lipopolysaccharide (LPS), a TLR4 agonist." (PMID 25390332, 2014). "Cho and colleagues suggested that high expression levels of the TLR4 gene induce MAPK and PI3K/Akt signaling pathways, contributing to nasal polyps remodeling." (PMID 38678138, 2024). "In a study conducted on primary nasal polyp culture, it was shown that steroids inhibited VEGF expression via the TLR4/Akt/NF-kB pathway." (PMID 36304979, 2022). "Previously, TLR4 activation by LPS leads to increased MMP-1 expression in small airway cells and nasal polyp-derived fibroblasts." (PMID 33199767, 2020). "Our study revealed that TLR4 is important for the production of pro-inflammatory cytokines and MMP-1 in nasal polyp organ cultures." (PMID 25390332, 2014). "In this study, we explored the role of TLR4 in gene expression of immune responses leading to IL-6, IL-8, and MMP-1 production after LPS stimulation in nasal polyp." (PMID 25390332, 2014). "To confirm the inhibitory effect of TLR4 antagonist on production of IL-6, IL-8, and MMP-1 in human tissues, we cultured nasal polyp organ cultures and treated the cells with LPS in the presence or absence of LPS-RS." (PMID 25390332, 2014). "Just like previously reported for primary healthy nasal epithelium, also here in epithelium of nasal polyps, despite the presence of TLR4 LPS did not induce IL-6 or IL-8." (PMID 27050744, 2016).
peripheral nerve injury (12 papers, 2009 to 2024). Injury to a peripheral nerve. "Additionally, some research found that a microglial TLR4 of the spinal cord is the key receptor to initiate microglial activation and cause chronic pain after peripheral nerve injury." (PMID 32848754, 2020). "Peripheral nerve injury has been shown to induce spinal cord neurogliocyte activation in chronic neuropathic pain models and is closely related to TLR4‐mediated NLRP3 inflammasome activation." (PMID 38415918, 2024). "We obtained miRNAs expression data related to neuropathic pain after peripheral nerve injury using the GEO database, and found that miR‐9 expression targeting TLR4 decreased after nerve injury compared to the sham operation group." (PMID 38415918, 2024). "GEO database was used to obtain microRNAs expression data involved in neuropathic pain following a peripheral nerve injury, which found that the expression of miR‐9 targeting TLR4 was decreased after nerve injury compared with the sham operation group." (PMID 38415918, 2024). "Toll-Like Receptor 4 (TLR4) is one of the prominent members of Toll-Like Receptors, having a critical role as a mediator of neuropathic pain throughout the process of peripheral nerve injury." (PMID 32641971, 2019). "As TLR-4 is described in peripheral nerve injury, a further investigation into its role in TJP internalization in neuropathic pain would be interesting." (PMID 30618565, 2018). "In this context, the present work aimed to investigate the influence of TLR2 and TLR4 on regeneration and functional recovery after peripheral nerve injury." (PMID 27222120, 2016). "Up-regulated heterodimer of TLR1/TLR2 upon stimulation and basal high level of TLR4 in both Schwann cells and sciatic nerve imply that TLR2 and TLR4 are crucial to Wallerian degeneration after peripheral nerve injury." (PMID 23984978, 2013). "Morphine relates to peripheral nerve injury, that induces neuropathic pain, via TLR4 signaling." (PMID 38052832, 2023). "TLRs appear to be recruited by TLR4 in early peripheral nerve injury." (PMID 30046125, 2018). "More recently a TLR4 antagonist showed efficacy in a mouse peripheral nerve injury model." (PMID 20011045, 2009). "Previous studies indicate that activation of sNAMs in the sensory ganglia, after peripheral nerve injury, depends on downstream signaling generated by the activation of TLR2, TLR4, and TLR9." (PMID 37254842, 2023).
RSV bronchiolitis (12 papers, 2006 to 2025). "Variants in genes such as TLR4 have been associated with RSV bronchiolitis, with some studies suggesting a role for the Toll-like receptor family in recognizing pathogen-associated molecular patterns (PAMPs) during RSV infection." (PMID 40873739, 2025). "This was associated with reduced neutrophil TLR4 in both compartments, with the lowest amounts for term infants with RSV bronchiolitis." (PMID 19497921, 2009). "Moreover, TLR4 polymorphisms Asp299Gly and Thr399Ile seem to be associated with an enhanced risk of developing severe RSV bronchiolitis." (PMID 32155831, 2020). "Additionally, other studies found that severe RSV bronchiolitis is associated with SNPs in TLR4 (rs4986790 and rs4986791)." (PMID 32375305, 2020). "This suggests that neutrophil TLR4 expression is deficient in these infants, which may explain why they develop severe RSV bronchiolitis." (PMID 19497921, 2009). "Genetic variants in genes (eg, TLR4, VDR, and CCR5) have been suggested to be associated with RSV bronchiolitis and the risk of asthma." (PMID 39299705, 2024). "Variants suggested to be associated with bronchiolitis or RSV bronchiolitis include polymorphisms in genes encoding surfactant proteins (SFTPA1, SFTPA2, SFTPD) and genes NKG2D and TLR4." (PMID 39299705, 2024). "TLR4 is activated during RSV bronchiolitis and genetic variations of TLR4 (Asp299Gly and Thr399Ile mutations) represent risk factors for RSV infection." (PMID 32375305, 2020). "After a careful check of their abstracts and/or full‐text reviews, 20 articles were excluded unrelated to TLR4 Asp299Gly (rs4986790), TLR4 Thr399Ile (rs4986791), CD14 C‐159T (rs2569190) polymorphisms and RSV bronchiolitis." (PMID 26901241, 2016). "Blood neutrophils from term infants with RSV bronchiolitis had less total TLR4 protein than preterm infants with RSV bronchiolitis (p = 0.005), and both had less than controls (p<0.04)." (PMID 19497921, 2009). "Blood neutrophils from preterm infants with RSV bronchiolitis had greater TLR4 mRNA expression than term infants with RSV bronchiolitis (p = 0.005) who had similar expression to controls (p = 0.625)." (PMID 19497921, 2009). "As in the blood, BAL fluid neutrophil TLR4 mRNA expression for term infants with RSV bronchiolitis was similar to that of controls (p = 0.6)." (PMID 19497921, 2009). "Blood neutrophil TLR4 mRNA expression of preterm infants with RSV bronchiolitis (566.27 (19.825)) was much greater than that of term infants with RSV bronchiolitis (p = 0.005) or controls (p = 0.021)." (PMID 19497921, 2009). "In the blood, neutrophil mRNA expression for TLR4 was similar for term infants with RSV bronchiolitis and control infants (34.84 (2.168) and 48.16 (2.758), respectively, p = 0.625; data expressed as mean (SEM) logfold ratio of TLR mRNA to L32 mRNA)." (PMID 19497921, 2009). "Although single-nucleotide polymorphisms (SNPs) in the CD14 and TLR4 genes have been associated with severe RSV bronchiolitis, a genetic link to recurrent or severe disease has not been described." (PMID 35429403, 2022). "The Buenos Aires study found that for this subgroup of infants with the TLR4 polymorphism, exposure to higher levels of LPS, due to being from a low-SES, rural region, provided a protective effect on the severity of RSV bronchiolitis even after adjusting for other risk factors." (PMID 33669911, 2021). "Recent investigations have also suggested a role of TLR4 in resolution of RSV-induced lung inflammation, and TLR4 mutations, leading to decreased TLR4 function, have been associated with increased severity of RSV bronchiolitis in infants." (PMID 24205331, 2013). "Similarly, BAL fluid neutrophil mRNA expression for TLR4 was greater for preterm infants with RSV bronchiolitis (4.38 (0.122)) than for term infants with RSV bronchiolitis (2.46 (0.129), p = 0.037) and for controls (1.12 (0.577), p = 0.034)." (PMID 19497921, 2009).
RSV bronchiolitis (continued). "TLR4 agonists are currently undergoing phase II clinical trials, so elucidating these mechanisms further will have important therapeutic implications for infants with severe RSV bronchiolitis." (PMID 19497921, 2009). "One of the striking findings of our study was that, in neutrophils of preterm infants with RSV bronchiolitis compared with controls, despite reduced protein expression of neutrophil TLR4 in the blood and BAL fluid, there were vastly increased levels of TLR4 mRNA in the blood." (PMID 19497921, 2009).
spinal cord injury (12 papers, 2012 to 2026). Penetrating and non-penetrating injuries to the spinal cord resulting from traumatic external forces (e.g., WOUNDS, GUNSHOT; WHIPLASH INJURIES; etc.). "Spinal cord injury (SCI) has been shown to trigger remote neuroinflammation in the frontal cortex via the HMGB1/TLR4/NF‐κB pathway, exacerbating neural damage and impairing functional recovery." (PMID 41555584, 2026). "Although TLR4 is one of the best characterized, its role in chronic stages after spinal cord injury (SCI) is not well understood." (PMID 38326029, 2024). "In the mouse model of spinal cord injury (SCI), CircRNA3616 upregulates TLR4 expression by sponging miR-137, and CircRNA3616 knockdown attenuates neuroinflammation via the TLR4/NF-κB pathway after SCI." (PMID 38138985, 2023). "Neuroinflammation plays a crucial role in the secondary phase of spinal cord injury (SCI), and is initiated following the activation of toll-like receptor 4 (TLR4)." (PMID 32826878, 2020). "In this study, we aimed to explore the regulatory mechanism of bone marrow mesenchymal stem cell-derived extracellular vesicles (BMSCs-EVs)-mediated miR-23b in lipopolysaccharide (LPS)-induced spinal cord injury (SCI) in vivo and in vitro by negatively regulating the TLR4/NF-κB pathway." (PMID 34663169, 2021). "Because TLRs might also have non-immune functions in spinal-cord injury (SCI), we aimed to investigate the influence of TLR2 and TLR4 on synaptic plasticity and glial reactivity after peripheral nerve axotomy." (PMID 23092428, 2012).
squamous cell carcinoma (12 papers, 2013 to 2024). A carcinoma arising from squamous epithelial cells. "Elevated TLR4 expression was significantly associated with histological type (adenocarcinoma higher than squamous cell carcinoma, P = 0.041), increased clinical TNM stage (P < 0.001), and presence of lymphatic invasion (P < 0.001)." (PMID 28484456, 2017). "In squamous cell carcinoma, activation of TLR4 reversed cetuximab-induced inhibition of proliferation, migration and invasion, increasing resistance to anti-EGFR therapy." (PMID 38067326, 2023). "In skin cancer, TLR4 also appears in keratinocytes and levels up during their progression to squamous cell carcinoma (SCC), whereas silencing of TLR4 led to the blockade of UV stress." (PMID 35780158, 2022). "TLR4 is an innate immune receptor with expression in human skin, keratinocytes as well as squamous cell carcinoma (SCC) of the skin." (PMID 28982115, 2017). "In squamous cell carcinoma, expression of TLR4 on epithelial cell membranes was significantly higher than in seborrheic keratosis, precancerous lesions, basal cell carcinoma and normal skin (P = 2.3e-5)." (PMID 23803172, 2013). "We also found that the membrane expression of TLR4 was higher in squamous cell carcinoma than normal skin and other tumors (P <0.01)." (PMID 23803172, 2013). "In addition, there is a correlation between TLR4 membrane expression and p65 nuclear localization during the progression from normal tissue to precursor lesions, to squamous cell carcinoma in human epidermal tumors." (PMID 29472602, 2018). "In basal cell carcinoma (BCC), TLR4 expression was seen on cell membranes of the cancerous epithelium and in highly malignant squamous cell carcinoma (SCC), there was a strong membrane positive expression of TLR4 on almost all of the cancerous epithelium." (PMID 23803172, 2013). "Summarizing the Results section, significant differences were observed in the expression of various TLRs (TLR-2, TLR-3, TLR-4, TLR-7, TLR-8, and TLR-9) on selected T and B cell subpopulations between the patients with squamous cell carcinoma (SCC) and the healthy controls." (PMID 39124797, 2024). "Different from the FnBPB on host epithelium cells, we found that highly expressed fnbpA in MRSA was able to activate the downstream TLR4/NF-κB/p38 MAPK/c-fos pathway, then promoting the proliferation of squamous cell carcinoma, indicating the different actions of FnBPA on cancer cells." (PMID 35859766, 2022).